AR (androgen receptor)
Diseases named in the same sentence as AR in open-access papers (continued):
Sharing a sentence is not in itself a finding about the gene and the disease.
breast carcinoma (continued). "Whole-genome expression data from primary breast cancers were obtained from public databases, screened for samples annotated for race information, and analyzed for associations with AR-status among breast cancer subtypes and racial groups." (PMID 29912871, 2018). "Exploratory analyses regarding the relationship between breast cancer risk factors and AR expression in normal tissue yielded few apparent associations." (PMID 30276234, 2018). "Several diseases such as prostate and breast cancer are also associated with alterations in androgen receptor functions." (PMID 28955675, 2017). "The androgen receptor translocates to the nucleus, where it interacts with β-catenin to trigger gene expression linked to breast cancer." (PMID 28956452, 2017). "Reduced AR expression in ER-positive disease can predict for an increased risk of relapse, breast-cancer associated death and worse DFS as well." (PMID 28245550, 2017). "Androgens signaling through AR is primarily antiproliferative in ERα-positive tissues and AR is associated with improved outcome in ERα-positive breast cancer." (PMID 28977936, 2017). "A recent clinical study showed that among 116 cases of invasive breast cancer AR was expressed in 56% of the cases and AR expression was significantly associated with early stage (p < 0.03) of breast cancer." (PMID 29254284, 2017). "In the current study, AR-515 phosphorylation is associated with decreased Ki67 in ER+ve tumours, confirming previous reports that AR is a good prognostic factor in ER+ve breast cancer due to an anti-proliferative effect." (PMID 28415597, 2017). "More patients with AR− tumors had received adjuvant chemotherapy and died from breast cancer-related causes compared to patients with AR+ tumors." (PMID 28643022, 2017). "Another example of AR significance is the confirmed increased risk for breast cancer in premenopausal women with elevated serum concentrations of testosterone, androstenedione and dehydroepiandrosterone sulfate." (PMID 28551687, 2017). "The combined hazard ratio for DFS of all included studies was 0.52, which was statistically significant, indicating a lower risk of recurrence for patients with AR-positive breast cancers." (PMID 28245550, 2017). "Some studies showed that in hormone receptor (HR)-positive (HR+) breast cancers, AR expression is associated with resistance to anti-estrogen therapies." (PMID 28957377, 2017). "Tamoxifen-resistance can occur in HR-positive breast cancers and AR signaling has been implicated in this process, leading to some clinical insight into the relationship between ER and AR signaling pathways." (PMID 28245550, 2017). "In conclusion, the present results indicate that AR and FOXA1 are closely associated in breast cancers, and distinctive clinicopathological features are presented in ER-positive tumors according to AR and FOXA1 status." (PMID 29137314, 2017). "Studies focused on integrating AR with other transcription factors such as ER are warranted to better understand the associations between AR and survival across breast cancer subtypes." (PMID 28643022, 2017). "High AR expression was associated with longer breast cancer specific survival (BCSS) and was an independent predictor of better outcome regardless of tumor size, grade and nodal stage." (PMID 28245550, 2017). "This review will aim to further clarify the complexities of the AR pathway in relation to breast cancer tumorigenesis, prognostic associations in relation to HR expression and HER2 amplification and potential therapeutic options." (PMID 28245550, 2017). "The SRA RNA is a non-coding RNA that strongly associated with breast cancer and participate in nuclear coactivation for several hormone-related systems, including the estrogen receptor, androgen receptor, progesterone receptor and thyroid hormone receptor." (PMID 26967566, 2016). "The association between AR expression and favorable outcome in ER positive breast cancer had been verified in various studies." (PMID 27340922, 2016).
breast carcinoma (continued). "ACSM1 has not been previously associated with PCa progression, but was reported as a potential marker for the invasive apocrine subtype of breast cancer, a rare subtype that is associated with AR+ status and poor differentiation." (PMID 27196083, 2016). "We find that AR has prognostic significance alone or in combination with HR status, and our data suggest that AR is associated with improved prognosis in luminal breast cancer and worse prognosis in TNBC." (PMID 27285752, 2016). "Studies are ongoing in breast cancer to investigate the effect of anti-androgen treatment in patients with AR positive tumors with loss of ERα and PR (ClinicalTrials.gov Identifier NCT00468715, NCT01889238)." (PMID 27384477, 2016). "Our findings underline a novel role for Lin28A in breast cancer development and activation of the AR axis." (PMID 27494865, 2016). "Other classification systems have split breast cancer into at least 10 subtypes, triple-negative breast cancer itself segregated into 6 subtypes and an additional AR (Androgen Receptor) positive variant of luminal breast cancer." (PMID 27259233, 2016). "NR0B1 is induced by AR-activation in ER+/MCF-7 breast-cancer cells and this causes aromatase down-regulation." (PMID 26894976, 2016). "Other reports however claim that high circulating levels of androgens are associated with increased breast cancer risk in both the premenopausal and postmenopausal setting and that elevated levels of AR are pro-metastatic." (PMID 26341737, 2015). "The upregulation of PSAP gene expression by HOXC11 in endocrine-resistant breast cancer cells was of interest primarily due to its association with tamoxifen resistance, but also because of its potential as an AR activator." (PMID 26341737, 2015). "Western blot analysis of a range of cell lines was performed to evaluate if there is an association between elevated levels of PSAP and nuclear AR protein in breast cancer cells." (PMID 26341737, 2015). "The androgen receptor (AR), another NR whose expression is strongly associated with ERα expression in breast cancer, inhibits expression of estrogen responsive genes in ERα-positive breast cancer cells." (PMID 26280373, 2015). "Other groups have also reported that AR expression was associated with favourable outcomes in patients with ER+ breast cancers." (PMID 26459317, 2015). "AR, a member of the steroid hormone receptor family, is expressed in more than 70% of breast cancers and has been implicated in breast cancer pathogenesis." (PMID 26039245, 2015). "Higher AR expression was significantly correlated with a decreased risk of recurrence and death when compared with patients having breast cancer with low AR levels." (PMID 24922532, 2014). "GCDFP-15 was furthermore strongly associated with AR and therefore enriched in the so-called molecular apocrine breast cancer subtype." (PMID 25070172, 2014). "In a cohort of 192 women with ER + breast cancers, a high ratio of AR:ER (≥2.0) indicated an over four fold increased risk for failure while on tamoxifen (HR = 4.43)." (PMID 24451109, 2014). "Over 70% of human breast cancers express AR, and AR positive cases are significantly associated with a low risk of tumor recurrence and patient death." (PMID 24505496, 2014). "This prediction is also supported by increased breast cancer susceptibility in women with reduced AR activity due to longer polymorphic CAG repeats." (PMID 25928046, 2014). "Large-scale retrospective reviews of AR status in breast cancer indicate a significant association between AR expression and overall survival, which remain significant even when controlled for ER status." (PMID 24922532, 2014). "Further research on the effects of sarcosine on HER-2 according to AR status will help elucidate the mechanism of association among these key molecules in breast cancer." (PMID 24884785, 2014).
breast carcinoma (continued). "Although it is well accepted that the expression of hormonal receptors such as ER and PR is associated with better outcome in women with breast cancer the role of AR has been less well investigated despite the fact that it is expressed in many breast cancers." (PMID 25510351, 2014). "Similar to ER and PR, AR expression is associated with a well-differentiated state and with more indolent breast cancers." (PMID 24451109, 2014). "In our studies, androgen-insensitive female mice (global ARKO model) have increased susceptibility to DMBA-induced mammary tumors, which demonstrates direct mammary gland-specific effects of androgens acting via the AR." (PMID 25928046, 2014). "Meta-analysis suggested that AR expression was associated with low risk of recurrence of breast cancer." (PMID 24324816, 2013). "In this paper we report for the first time the association of Leydig cell tumour and AR+ve breast cancer in a woman with a long-term history of infertility, dramatic virilism and erythrocytosis." (PMID 23816265, 2013). "In conclusion, AR expression is associated with a less aggressive phenotype and a good prognosis in patients with ERα-positive breast cancer." (PMID 24403250, 2013). "Here, we present the case of a middle-age woman affected by an occult androgen secreting tumour of ovary causing erythrocytosis and by a breast cancer expressing only androgen receptors (AR) and, at lower extent, progesterone receptors (PR)." (PMID 23816265, 2013). "We were interested to determine if AR deletion also affected the susceptibility of male breast cancers, since men with partial or complete androgen insensitivity (AIS) have an elevated risk of breast cancer." (PMID 23593223, 2013). "Several studies have demonstrated that the positivity for AR expression is associated with a better prognosis, especially in patients with ERα-positive breast cancers." (PMID 24403250, 2013). "The present analysis indicated that AR expression was associated with lower risk of recurrence in patients with all breast cancer types and better OS in cases with ER positive." (PMID 24324816, 2013). "It has previously been reported that global AR knockout increases the susceptibility of female mice to DMBA-induced mammary tumors." (PMID 23593223, 2013). "AR expression was evaluated by immunochemistry in a cohort of 528 postmenopausal breast cancer patients previously examined for the association of serum testosterone levels with patient and tumor characteristics." (PMID 23241075, 2012). "Androgen receptor (AR) has been detected in female breast cancer and is often associated with apocrine differentiation." (PMID 22988495, 2012). "In hormone-responsive cells expressing both AR and ER (α and/or β), such as prostate and breast cancers, AR/ER/Src association plays a crucial role in activation of Src signals triggered by EGF and/or sex hormones." (PMID 22922989, 2012). "In primary breast carcinomas, including triple-negative breast cancer, AR expression was interestingly associated with a significantly better disease free interval and overall survival." (PMID 23148692, 2012). "In this paper we show that AR expression is significantly associated with 10-year survival outcome in patients with Stage III breast cancer." (PMID 22471922, 2012). "For example, in luminal breast cancers expressing AR, the AR expression is associated with better prognosis." (PMID 22321971, 2012). "Six haplotype-tagging single-nucleotide polymorphisms in the AR, and the resulting AR diplotypes, were examined in relation to breast cancer patient characteristics, tumour characteristics, disease-free survival, and response to endocrine treatment." (PMID 22033271, 2011). "If HE3235 is found to be active against breast cancer in humans, decreased ERα and AR expression are associated with improved prognosis and reduced escape from therapy." (PMID 22332014, 2011).
breast carcinoma (continued). "Others have shown that the AR is a direct repressor of ERα signalling in breast cancer cells due to an association between AR and the oestrogen response elements." (PMID 22033271, 2011). "The frequencies of the five most common AR diplotypes were also similar to those found in young Swedish women from high-risk breast cancer families." (PMID 22033271, 2011). "Shorter alleles of the AR gene would be associated with a better response to circulating androgens, possibly resulting in better "repression" of breast cancer development and/or progression." (PMID 20831839, 2010). "The relationship has been examined in several case-control studies in different populations; some have related longer CAG repeats with an increase in breast cancer risk whereas others have limited the impact of AR-CAG repeat on Breast Cancer." (PMID 20831839, 2010). "Transfection of MDA-MB-231 breast cancer cells with either functionally impaired AR variants or the DNA-binding domain of the AR indicated that the latter is both necessary and sufficient for inhibition of ERα signalling." (PMID 20831839, 2010). "Whereas in women of Greek decent, an association for breast cancer risk with short alleles (≤22 repeats) for the AR gene was observed." (PMID 20831839, 2010). "In the present study we also investigated the possible relationship between AR expression and both MMPs and TIMPs expression in tumors, which have been associated with an aggressive behaviour and a poor prognosis in breast cancer patients." (PMID 18507821, 2008). "In a previous study, shorter alleles of the CAG repeat polymorphism in exon 1 of the AR gene were associated with decreased risk of disease in women with a family history of breast cancer in the NHS." (PMID 16987421, 2006). "Due to the low numbers of premenopausal women in our study, we cannot exclude the AR gene as a susceptibility locus for breast cancer occurring before menopause." (PMID 16987421, 2006). "Here, we report on the results of a large and comprehensive study of the association between genetic variation in the AR gene and risk of breast cancer in the National Cancer Institute Breast and Prostate Cancer Cohort Consortium (BPC3)." (PMID 16987421, 2006). "The 95% confidence intervals in our study were narrow and exclude a substantial association between common variants in the AR gene with breast cancer risk." (PMID 16987421, 2006). "Women with germline BRCA1 mutations who carry at least one AR allele with 28 or more repeats have been reported to have an earlier age at onset of breast cancer." (PMID 15743497, 2005). "There is evidence that suggests an association between longer AR CAG repeat length – representative of less active AR – and breast cancer risk at the population level (for review, see Lillie and coworkers)." (PMID 15743497, 2005). "A previous study has suggested that BRCA1 carriers with longer lengths of the CAG repeat in the androgen receptor (AR) gene are at increased risk of breast cancer (BC)." (PMID 11437399, 2001). "In HR+ breast cancers, AR expression has been associated with less aggressive features." (PMID 40734715, 2025). "The similarities between human breast cancer and canine mammary tumors make these animal models particularly useful for studying the mechanisms underlying AR signaling and for evaluating the efficacy of novel AR-targeted therapies." (PMID 40286049, 2025). "A positive association was also observed between APP and AR in breast cancer tissues." (PMID 41614805, 2025). "Moreover, specific AR variants have been identified as potential predictors of breast cancer aggressiveness." (PMID 40734715, 2025). "In addition to AR, tumor-associated neutrophils (TANs) have garnered attention for their role in the breast cancer tumor microenvironment." (PMID 40734715, 2025). "The ability to monitor AR expression in canine mammary tumors may enable the identification of high-risk cases, leading to more targeted therapeutic approaches." (PMID 40286049, 2025).
breast carcinoma (continued). "In addition to its impact on tumor progression, AR expression in canine mammary tumors has been associated with favorable prognostic factors in certain subtypes." (PMID 40286049, 2025). "Interestingly, AR expression in canine mammary tumors has also been linked to the presence of estrogen and progesterone receptors, highlighting the potential for hormonal crosstalk to regulate tumor behavior." (PMID 40286049, 2025). "APOBEC3A and APOBEC3B have been linked to persistent cell evolution and therapy resistance in lung cancers, and APOBEC3B has been linked to resistance against androgen receptor (AR)-targeted therapy and Tamoxifen in prostate and estrogen receptor-positive (ER+) breast cancers." (PMID 38254863, 2024). "Androgen receptor (AR) is also frequently present in breast cancer cells, and intratumoral androgens are important for the progression of breast cancers while also being closely associated with resistance to endocrine therapies in breast cancers." (PMID 39682229, 2024). "It suggests that prenatal hormonal exposure may predispose individuals to develop certain types of breast cancer, potentially through mechanisms that affect AR and ER expression patterns." (PMID 38877071, 2024). "By analyzing miRNA expression data from AA and EA breast cancer patients, we sought to identify miRNAs that could potentially contribute to the observed loss of AR expression and racial disparities in disease outcomes." (PMID 39769441, 2024). "Nonetheless, as ~20% of ER/PR-negative BRCA1mut breast cancers express AR, the modulation of AR may offer new treatment options for these high-risk cancers." (PMID 36831687, 2023). "Indeed, AR expression is associated with a better outcome in ER+ breast cancer patients, including high-risk ER+ cancers undergoing endocrine therapy." (PMID 37686282, 2023). "The AR/ER ratio has been shown to be associated with outcomes in ER+ breast cancer patients." (PMID 36982683, 2023). "Thus, we aimed to better clarify the underlying mechanisms by which androgen/AR signaling exerts anti-proliferative/pro-apoptotic effects in breast cancer cells." (PMID 37686282, 2023). "AR’s specific role in breast cancer is currently widely unknown and its association to signaling pathways such as CDK4/6, CYP17 lyase, and PI3K can be a huge development in the treatment of TNBC." (PMID 38067367, 2023). "In agreement with a pattern recently reported in primary breast cancer, several genes from the highly intercorrelating gene cluster associated to hormone responsiveness (AR, PGR, ER signaling, ESR1, and FOXA1) emerged as interesting prognostic markers for MBC, both when expressed in PT and in DM." (PMID 38449790, 2023). "Therefore, the expression of the AR is associated with specific immunological profiles in the breast cancer microenvironment at both the gene and protein expression levels." (PMID 37681860, 2023). "The physiologic basis for this increase in the risk of breast cancer from exogenous androgens may be related to the conversion of androgens to estrogens or more directly with effects mediated through the androgen receptor." (PMID 37951051, 2023). "We found a significant association between AR expression and primary breast cancer subtype." (PMID 37345085, 2023). "This study aimed to explore whether there is an association between androgen receptor (AR) expression and ultrasound, clinicopathological features and prognosis of breast cancer." (PMID 36929229, 2023). "This incongruency in AR function in HR+ BCa may be associated with its level of expression and/or the stage of disease; the exact consequence remains to be defined in breast cancer." (PMID 38203649, 2023). "Anticancer therapy may utilize androgen receptor (AR) signaling pathway inhibition, which has been implicated in the carcinogenesis and metastasis of hormone-related tumors, e.g., prostate and breast cancer." (PMID 38139858, 2023).